IL6 (interleukin 6)
Diseases named in the same sentence as IL6 in open-access papers (continued):
Sharing a sentence is not in itself a finding about the gene and the disease.
depression (continued). "Vagus nerve stimulation (VNS): Clinical trials have shown that VNS reduces depressive symptoms in treatment-resistant depression while modulating systemic inflammation, with documented reductions in TNF-α and IL-6 levels." (PMID 40218134, 2025). "A thorough meta-analysis established a clear link between increased concentrations of IL-6 and CRP and the presence of major depressive disorder." (PMID 40363978, 2025). "Depression score and the serum concentrations of TNF-α, IL-6, and hs-CRP were decreased after intervention in the omega-3 fatty acids group compared with the placebo group." (PMID 39997208, 2025). "Animal studies have indicated that the IL-6/STAT3 signaling pathway is involved in depression-like behaviours and that STAT3 controls IL-6-dependent SERT expression." (PMID 40115872, 2025). "Multiple studies have shown elevated levels of pro-inflammatory cytokines such as interleukin (IL)-1β, IL-6, tumor necrosis factor-α (TNF-α), and C-reactive protein (CRP) in patients with depression, particularly in those with treatment-resistant depression." (PMID 41303496, 2025). "Our findings suggest that sertraline treatment can significantly affect the levels of IL-6 and TNF-α in patients with depression." (PMID 41023687, 2025). "Escitalopram can reduce the levels of pro-inflammatory cytokines—IL-1β, IL-1ra, IL-2, IL-4, IL-6, IL-8, IFN-y, TNF-α in the serum of patients suffering from depression, while simultaneously increasing the level of anti-inflammatory IL-10." (PMID 41302150, 2025). "In our study, XCHT was proven to alleviate depressive disorders by downregulation of IL‐1β, TNF‐α, and IL‐6 inflammasome, modulating the immune system by inhibiting Iba‐1 and GFAP overexpression, making it a promising candidate for the treatment of depression." (PMID 39981856, 2025). "The outcomes studied included plasma concentrations of NO, depression ratings, brain-derived neurotrophic factor (BDNF), interleukin-1β, interleukin-6, TAC, and MDA." (PMID 41228407, 2025). "Several meta-analyses have consistently demonstrated elevated levels of proinflammatory markers, including IL-6, TNF-α, and CRP, in subsets of patients with depression." (PMID 41155383, 2025). "Wendan decoction effectively reduced the levels of pro-inflammatory factors IL-1β, IL-6, and TNF-α, with similar anti-inflammatory effects reported in depression treatment, underscoring its multimodal therapeutic action." (PMID 40713709, 2025). "Further statistical linear regression analysis shows that IL-6 (B = 0.171, p = 0.000) and TNF-α (B = 0.039, p = 0.012) are statistically significant predictors (p < 0.05) of depression intensity on the Hamilton depression scale in group I." (PMID 40699818, 2025). "This study confirmed that the levels of IL-6 and TNF-α in patients with depression significantly decreased before and after sertraline monotherapy." (PMID 41023687, 2025). "In mice models exposed to chronic unpredictable stress, an increased expression of cytokines IL-1β, IL-6, and TNF-α in the amygdala was observed and mice presented symptoms of depression and anxiety disorder." (PMID 40141110, 2025). "Increased levels of cytokines (e.g., IL-6 and TNF-α) are often correlated with depressive symptoms, supporting the idea that inflammation is an essential component of the etiology of depression." (PMID 40305200, 2025). "Most present studies mainly focused on exploring the relationship of IL-1b, IL-2, IL-6, and TNF-a, with depression." (PMID 40530060, 2025). "Elevated levels of pro-inflammatory cytokines such as IL-6 and TNF-α in major depressive disorder (MDD) further skew bone remodeling toward resorption." (PMID 41007423, 2025). "The model group exhibited significantly higher levels of IL-1β, IL-6, and TNF-α compared to the blank group (p < 0.01), indicating that the depression model successfully induced systemic inflammatory responses." (PMID 41464995, 2025).
depression (continued). "Our findings revealed significantly elevated circulating levels of IL-6, IFN-γ, IL-17, TNF-α, IL-10, and IL-27 in individuals with depression compared to healthy controls." (PMID 41561993, 2025). "Contributing factors include chronic pain, stiffness, elevated IL-6 and TNF-α, depression, anxiety, and medication side effects." (PMID 41153815, 2025). "Growing evidence indicates brain inflammation in depression in the form of heightened translocator protein (TSPO) expression, and increased IL-6 and TNF-α in the cerebrospinal fluid (CSF)." (PMID 39959848, 2025). "The results for anthropometric variables, body composition, V̇O2peak, Ki67, IL‐6, CRP protein, and depression from T1 to T2 are shown in." (PMID 40859620, 2025). "One previous study reported that expression of IL-1β was increased as well as IL-6 and TNF-α in PFC of the teenage suicide depression patients, consistent with peripheral findings." (PMID 40179065, 2025). "A grouped meta-analysis found significant positive associations between concentrations of TNF-a, IFN-γ, IFN-γ PHA, IL-10, IL-10 (LPS and PHA), IL-6, IL-6 (LPS and PHA) and levels of depression in individuals with MS." (PMID 39867847, 2025). "Several cytokines including Interleukin 6 (IL6), C-reactive protein (CRP) and Tumor Necrosis Factor alpha (TNFα) have elevated levels in depression." (PMID 40352929, 2025). "In rodent models of depression induced by chronic unpredictable stress, expressions of TNF, IL-1β, IL-6, cyclooxygenase-2 (COX-2), and inducible nitric oxide synthase (iNOS) are elevated in the hippocampus." (PMID 40710585, 2025). "Elevated IL-6 and TNF-α levels, commonly observed in individuals with depression, contribute to inflammation and HPA axis activation, influencing mood regulation, neurotransmitter metabolism, and neural plasticity, thereby exacerbating depressive symptoms." (PMID 39949541, 2025). "Recent research has revealed a crucial role for pro-inflammatory cytokines, including interleukin (IL)-1β, IL-6, and tumor necrosis factor (TNF)-α, in stress-induced depression." (PMID 40612748, 2025). "Recent studies have shown that peripheral immune-to-brain signaling can disrupt neural homeostasis via cytokines such as IL-6 and TNF-α and lead to depression." (PMID 41425563, 2025). "A growing amount of data indicates that the overproduction of pro-inflammatory cytokines, such as IL-1β, IL-6, and TNF-α, by immune cells within the brain, plays an important role in the onset and progression of depression." (PMID 40612748, 2025). "Depression can arise in endotoxic shock due to a systemic inflammatory response mediated by cytokines such as TNF-α and IL-6." (PMID 41300522, 2025). "Pro-inflammatory cytokines, such as IL-6, TNF-α, and IL-1β, are among the most studied biomarkers of inflammation in depression." (PMID 40004109, 2025). "In agreement, plasma IL-6 levels showed a reduction 26 days following the initiation of ketamine infusions and after 6 esketamine applications, and IL-6 levels were associated with a reduction in symptoms of depression but not with the changes in anhedonia scores." (PMID 40001598, 2025). "Clinical and research data have reported that inflammatory markers in both the blood and the brain, including interleukin IL-1β, IL-6, and tumor necrosis factor TNF-α, are markedly elevated in individuals with major depression." (PMID 40006068, 2025). "The level of interleukin (IL)-1β, IL-6, tumor necrosis factor α (TNF-α), and depression-like behavior in rats showed that the CP/CPPS complicated with depression model was established successfully." (PMID 40576719, 2025). "Inflammatory markers such as IL-1β, IL-6, TNF-α, IL-18, and CRP are commonly observed in animal models of depression." (PMID 40277932, 2025). "Increased evidence points to the number of immune-related genes, such as IL1B, IL6, and TNF, that connect epilepsy and depression through inflammatory pathways." (PMID 40941042, 2025).
depression (continued). "Inflammatory biomarkers such as C-reactive protein (CRP), interleukin-6 (IL-6), and tumor necrosis factor-alpha (TNF-α) are elevated in both periodontitis and depression, raising the possibility of a shared inflammatory pathway." (PMID 40656387, 2025). "Exercise also has anti-inflammatory effects, lowering levels of pro-inflammatory cytokines such as IL-6 and TNF-α, which are elevated in depression, helping to normalize hypothalamic–pituitary–adrenal axis activity and reducing hyperactivity and stress." (PMID 41562726, 2025). "Moreover, evidence indicates that depression may precede and augment pro-inflammatory cytokines, including interleukin-6 (IL-6) and C-reactive protein (CRP), potentially contributing to the development of cardiometabolic and other age-related diseases in healthy older adults." (PMID 41039395, 2025). "Inflammatory markers such as interleukin-6 (IL-6) and tumor necrosis factor-alpha (TNF-α) are consistently elevated in patients with depression." (PMID 41346637, 2025). "Future research endeavors will focus on integrating bone turnover markers, inflammatory factors (e.g., IL-6, TNF-α), and genetic data to elucidate the biological pathways linking depression, osteoporosis, and mortality." (PMID 40988243, 2025). "Its root extract suppresses the expression of inflammation-related proteins such as cyclooxygenase-2, iNOS, IL-6, IL-1β, and TNF-α, while modulating neuroendocrine and neurotransmitter systems to exert neuroprotective effects in mouse models of depression." (PMID 40936908, 2025). "C3, which shows a positive correlation with TNF-α, IL-6, and IL-1β, can suppress inflammation in the context of CSVD with depression." (PMID 40584618, 2025). "The norepinephrine transporter is involved in hypertension and depression by regulating TNF-α and IL-6." (PMID 40230380, 2025). "Next, we examined social and depression-like phenotype and the expression of pro-inflammatory markers (TNF-α, IL-1β, NF-κB1, and IL-6) in the ventromedial prefrontal cortex (vmPFC) and hippocampal CA1 brain regions." (PMID 40558565, 2025). "In the univariate analysis, IL-6, CRP, ESSPRI total, ESSPRI pain, and ESSPRI fatigue were statistically significant for the OR for depression." (PMID 40822847, 2025). "Furthermore, the dysregulation of IL-6 along with other pro-inflammatory cytokines, such as IL-1 and TNF-α, can lead to nerve inflammation, which is associated with neurodegenerative diseases such as Alzheimer’s disease (AD), Parkinson’s disease (PD), depression, and multiple sclerosis (MS)." (PMID 40305179, 2025). "The anti-inflammatory activity of omentin resides in its ability to downregulate the production of IL-1β, IL-6, and TNF-α, which are often involved in depression’s pathogenesis." (PMID 41375608, 2025). "Another randomized, double-blind control study showed a decrease in IL-6 and tumor necrosis factor-alpha (TNF-α) levels just after 40 min and was correlated with a lower Montgomery-Asberg Depression Rating Scale (MADRS) score." (PMID 40806626, 2025). "Elevated levels of IL-6 and TNF-α in individuals with depression contribute to insulin resistance and pancreatic beta-cell dysfunction, creating a vicious cycle of metabolic and psychological dysregulation." (PMID 40218134, 2025). "Refining Biomarkers: Further research is needed to validate biomarkers such as CRP, IL-6, and HRV for clinical use in differentiating depression from cardiac pathology." (PMID 40218134, 2025). "The results also showed a positive correlation between the serum concentrations of TNF-α, IL-6, and hs-CRP with depression scores before and after intervention in both groups." (PMID 39997208, 2025). "Concurrently, decreased apoA1 and PON1 levels in depression compromise HDL’s anti-inflammatory capacity, allowing IL-6-driven neuroinflammation to persist." (PMID 40511456, 2025).
depression (continued). "Pro-inflammatory cytokines levels, such as IL-1, IL-6, and tumor necrosis factor (TNF) -α, were significantly raised in depression patients compared with normal subjects 35,36." (PMID 40520890, 2025). "Meta-analytic evidence indicates elevated levels of IL-6, CRP, and TNF-α in individuals with depression." (PMID 41333345, 2025). "After nine iterations the final model included BMI, IL‐6, PCS, PANAS positive, DSQ distress and depression, cPPT, and TSP and explained 68% (F = 5.7, p < 0.001) of the variability in DOMS pain after habitual sleep with and adjusted R2 of 56%." (PMID 39289848, 2025). "In this study, compared to the control group, CRS mice with anxiety and depression showed significantly increased expression levels of Notch1/Hes-1, TNF-α, IL-1β, and IL-6 in the hippocampal region." (PMID 39789446, 2025). "Pro-inflammatory proteins identified include TNF-α, IL-6, IL-1β and C-reactive protein (CRP) which have been found to be increased in individuals with depression." (PMID 39867847, 2025). "TAK-653’s apparent regulation of IL-6, cortisol, and BDNF aligns with emerging paradigms of depression as a disorder of neuroimmune crosstalk." (PMID 40564108, 2025). "Taken together, these findings highlight the significant role of inflammation, particularly mediated by cytokines like IL-2, IL-6, and IFN-γ, in the pathogenesis of both COPD and depression." (PMID 40724725, 2025). "The IL-6/STAT3 pathway has been shown to facilitate the formation of neuropathic pain and comorbid depression in spinal nerve injury (SNI) rats." (PMID 40093024, 2025). "By inhibiting the cGAS-STING pathway, exercise reduces the expression of interferon beta-1 (IFNβ1) and other pro-inflammatory cytokines IL-6 and TNF-α, thereby decreasing the inflammatory response, improving mitochondrial function, and alleviating depression." (PMID 40699781, 2025). "Most of the research used outcome indicators such as depression and anxiety scales and CRP, IL-6, and TNF-α levels." (PMID 41010394, 2025). "IL-1, IL-6, and TNF-α, on the other hand, lead to neural progression and depression through their pathways." (PMID 40530060, 2025). "Another meta-analysis reported that individuals with depression exhibited notably elevated blood levels of CRP, IL-6, and TNF-α relative to healthy controls, with effect sizes ranging from moderate to large (0.54 to 1.97)." (PMID 40363978, 2025). "In a murine LPS-induced depression model, the MAOI tranylcypromine was shown to reduce the expression of pro-inflammatory cytokines IL-1β, IL-6, and TNF-α." (PMID 40277932, 2025). "Depression score and the serum concentrations of tumor necrosis factor-α (TNF-α), interleukin-6 (IL-6), and high-sensitivity C-reactive protein (hs-CRP) were assessed before and after the study." (PMID 39997208, 2025). "Proinflammatory cytokines, including interleukin (IL)‐6 and tumor necrosis factor (TNF)‐α, demonstrated good performance in accurately predicting depression in these patients." (PMID 40387308, 2025). "Serum IL-6 and TNF-α levels are elevated in patients with depression, which can pass via the blood–brain barrier, triggering neuro-inflammation." (PMID 39856996, 2025). "Cumulative studies have demonstrated peripheral proinflammatory markers, such as CRP, IL-6, IL-1β, and TNF-α, were significantly increased in individuals suffering from depression." (PMID 40108901, 2025). "Elevated IL-6 levels are found in both COPD and depression, with IL-6, IFN-γ, and IL-2 involved in producing symptoms of depression." (PMID 40724725, 2025). "Increased levels of depression-related pro-inflammatory cytokines (such as TNF-α, IL-6, and IL-1) can activate the hypothalamic-pituitary-adrenal (HPA) axis and the sympathetic nervous system via various pathways." (PMID 40270731, 2025).
depression (continued). "Research conducted on patients suffering from depression disorders indicate in serum the consistently increased levels of pro-inflammatory cytokines such as TNF-α and IL-6, with their combined activity leading to systemic inflammation." (PMID 40722844, 2025). "An increase in the inflammatory markers, like C-reactive protein (CRP), interleukin (IL)-6, and tumor necrosis factor alpha (TNF-α), is often observed in patients with depression compared with healthy individuals." (PMID 38957737, 2024). "For instance, a study on adolescent patients with the first-episode of depression highlighted a correlation between pro-inflammatory TNF- and IL-6 signaling and increased anti-inflammatory activity mediated by IL-10 and IL-4." (PMID 38912378, 2024). "This often manifests as abnormal cytokine concentrations, such as elevated levels of interleukin-6 (IL-6) and tumor necrosis factor-α (TNF-α), in patients with depression." (PMID 39329797, 2024). "Ferulic acid inhibited the activation of microglia and significantly decreased the contents of IL-1β, IL-6, and TNF-α in the prefrontal cortex of the CUMS-induced depression mouse model by inhibiting the NLRP3/caspase-1/NF-κB pathway." (PMID 38915473, 2024). "Studies consistently demonstrate elevated levels of pro-inflammatory cytokines, such as interleukin-6 (IL-6) and tumour necrosis factor alpha (TNF-α), in the brains and blood of individuals with PD and depression." (PMID 38337395, 2024). "Another relatively consistent finding is the detrimental effects of increased IL6 signaling to SCZ, MDD, depressive sub-symptoms and depression." (PMID 38272880, 2024). "Transplantation of OP-modulated microbiota into CUMS receptor mice alleviated depression and anxiety, reduced elevated cytokine levels (TNF-α, IL-1β, IL-6, etc.), and restored histopathological damage in the colon." (PMID 38983862, 2024). "Researchers have found a strong correlation between elevated plasma IL-6 levels and HPA axis dysfunction in tumor patients diagnosed with depression." (PMID 38716256, 2024). "Inflammatory cytokines are increased in depressed patients and mouse models of depression, and TNF-α and IL-6 expression is elevated in the prefrontal cortex and orbitofrontal cortex of depressed patients who die by suicide." (PMID 38902845, 2024). "Pro-inflammatory factors such as interleukin-1β (IL-1β), interleukin-6 (IL-6), and tumor necrosis factor-alpha (TNF-α) are regarded as depression biomarkers." (PMID 38389919, 2024). "Acute phase proteins, such as C-reactive protein and haptoglobin, as well as inflammatory cytokines like interleukin-1 (IL-1), interleukin-6 (IL-6), and TNF-alpha were shown to be typically related with illness behavior and depression, respectively." (PMID 38315652, 2024). "Activation of GPR55 using O-1602 inhibited the activation of the inflammasome, normalizing the increased expression of IL-1β (IL-6 and TNF) and the decreased expression of IL-4 and IL-10, respectively reducing the depression- and anxiety-like behavior." (PMID 38796643, 2024). "The predictive value of the cytokines IL-1α, IL-6, and TNF-α in the discrimination of patients with severe depression was assessed based on the AUC values, which is also presented graphically by the ROC curve." (PMID 39595067, 2024). "In our results, BDNF, NO, IL-6, and 5-HT showed the same trend results as previously reported, which validates the model’s success and demonstrates the role of PPT in improving depression." (PMID 39062817, 2024).